CST3 (cystatin C)
Diseases named in the same sentence as CST3 in open-access papers (continued):
Sharing a sentence is not in itself a finding about the gene and the disease.
diabetic nephropathy (continued). "We assessed the causal effect of cystatin C together with other five serum biomarkers including KIM-1, GDF-15, TBIL, uric acid, and Scr on diabetic nephropathy by Mendelian randomization (MR) analysis." (PMID 36482996, 2022). "Although dozens of studies have investigated the relationship between the content of serum cystatin C (Cys-C) and diabetic nephropathy (DN), the results are still controversial." (PMID 35655297, 2022). "The concentration of serum cystatin C (index test) and traditional markers of diabetic nephropathy, serum creatinine, and urinary microalbumin (the reference standard) were estimated." (PMID 33996155, 2021). "Baseline parameters of potential subjects such as HbA1c, blood pressure, Advanced Glycation Endproduct (AGE), soluble receptor for AGE (sRAGE), Nε-Carboxymethyllysine (Nε-CML), and Cystatin C were assessed for possible correlation with diabetic nephropathy." (PMID 30227659, 2018). "Eight weeks of high-dose Tocovid did not improve HbA1c, blood pressure, serum AGE, sRAGE, Nε-CML, and Cystatin C in patients with diabetic nephropathy." (PMID 30227659, 2018). "The results of present study show that IL-19 levels was significantly elevated in the patients with diabetic nephropathy and was associated with Hs-CRP, Cystatin C, UAE and HbA1c." (PMID 28201997, 2017). "The experiment was finished at an early stage of diabetic nephropathy as proven by plasma cystatin C levels which were lower in STZ-treated animals compared with non-diabetic controls." (PMID 22900035, 2012). "Furthermore, a meta-analysis indicated that probiotics have the potential to reduce various indicators of kidney disease in individuals with diabetic nephropathy, including blood urea nitrogen, serum creatinine, cystatin C, and UACR." (PMID 39939503, 2025). "The present study also found significant lipoprotein abnormalities in T2DM patients with diabetic nephropathy when compared with those without diabetic nephropathy, and these lipoprotein abnormalities were significantly associated with serum cystatin C levels." (PMID 37082121, 2023). "Our results suggest that measurements of serum cystatin C accompanied by calculation of eGFR with the use of CKD-EPICycC equation may be useful already at the earlier stages of diabetic kidney disease." (PMID 30158836, 2018). "IL-19 is significantly positive correlated with UAE and Cystatin C. IL-19 may play an important role that contributes to the progression of diabetic nephropathy." (PMID 28201997, 2017). "Patients in higher quartiles were more likely to have ischaemic/hypertensive nephropathy or diabetic kidney disease as their primary renal disease and less likely to have glomerulonephritis, and also had worse renal function (lower eGFR and higher cystatin C), higher CRP, and higher serum cFLC." (PMID 28403201, 2017). "In addition to its use as a diagnostic marker for AKI, a type of kidney injury thought to be driven mainly by tubular injury, urinary cystatin C was also shown to predict progression of diabetic nephropathy." (PMID 25310591, 2014). "Four of the peaks that were discovered have been identified as transthyretin, apolipoprotein A1, apolipoprotein C1 and cystatin C. Several yet unidentified proteins discovered by this novel approach appear to have more potential as biomarkers for diabetic nephropathy." (PMID 20205888, 2010). "The present study aimed to establish a correlation between diabetic nephropathy with HbA1c, blood pressure, AGE, sRAGE, Nε-CML, and Cystatin C. The second aim is to investigate whether high-dose Tocovid will have an effect on diabetic nephropathy assessed by UACR, serum creatinine, and eGFR." (PMID 30227659, 2018). "As is common in the pathophysiology of CKD, such as diabetic nephropathy, we often diagnose CKD later through elevated kidney biomarkers serum creatinine or cystatin C when the disease has already far progressed and irreversibly damaged the kidney." (PMID 38287274, 2024).
diabetic nephropathy (continued). "Furthermore, cystatin C is a better discriminator between type 2 diabetic patients with normoalbuminuria or microalbuminuria and its quantification is useful in the early identification of diabetic nephropathy allowing for the appropriate intervention and management." (PMID 33401560, 2021). "Binary logistic regression was used to determine the odds of diabetic nephropathy in relation to the HbA1c, SBP, DBP, AGE, sRAGE, Nε-CML, and Cystatin C levels." (PMID 30227659, 2018). "A variety of alternative biomarkers such as cystatin C is shown to correlate with GFR especially at the early stage of diabetic kidney disease." (PMID 28494191, 2017). "Sixth, serum cystatin C has also been shown to be an early marker of diabetic kidney disease, but our results showed that cystatin C remained elevated in STDR in a subgroup of patients with normal eGFR." (PMID 35511139, 2022). "While some researchers suggest using cystatin C for diabetic nephropathy, the othersclaim that it is not significant." (PMID 33599678, 2021). "Although albuminuria remains one of the most significant predictors of renal decline, other markers, such as serum and urine NGAL, serum cystatin C, urine KIM-1, IgG, and transferrin, may add to the early diagnosis of diabetic kidney disease." (PMID 30158836, 2018). "Patients with microalbuminuria present higher values of urinary cystatin C than those without microalbuminuria, urinary cystatin C having a predictive role for the progression of diabetic nephropathy (DN)." (PMID 27413755, 2016). "Therefore, this study aimed to explore the clinical significance of serum cystatin C and lipid profile abnormalities for the differential diagnosis of diabetic nephropathy and non-diabetic nephropathy in patients with T2DM." (PMID 37082121, 2023). "Further, microalbuminuria and diabetic nephropathy patients marked the excretion of Ig kappa chain V–II, protein 25, Ig lambda 2 chain region, Alpha 1 acid glycoprotein 1, Apolipoprotein A1, transthyretin/prealbumin, Ig kappa C chain region, AMBP, Cystatin C, zinc alpha 2 glycoprotein and Ubiquitin." (PMID 31131043, 2019). "The present study found significant serum cystatin C and lipoprotein abnormalities in T2DM patients with diabetic nephropathy when compared with those without diabetic nephropathy, and these lipoprotein abnormalities were significantly associated with serum cystatin C levels." (PMID 37082121, 2023).
metabolic syndrome (47 papers, 2012 to 2026). A cluster of metabolic risk factors for CARDIOVASCULAR DISEASES and TYPE 2 DIABETES MELLITUS. "Cystatin C levels are associated with various cardiovascular risk factors, including dyslipidemia, cholesterol levels, obesity, and metabolic syndrome." (PMID 39927731, 2025). "Cystatin C is a marker of renal function that has recently been implicated in metabolic syndrome development and can also be a predictive indicator of cardiovascular disease." (PMID 37508717, 2023). "Some studies have shown that cystatin C is important in diagnosing metabolic syndrome and determining risk." (PMID 35657129, 2022). "Background and objectives: This study aimed to assess the clinical significance of serum cystatin C in the early diagnosis of renal injury and its association with dyslipidemia in young T1D patients." (PMID 35208542, 2022). "A cross-sectional study on 925 patients with dyslipidemia and 26% prevalence of metabolic syndrome has revealed that cystatin C is associated with metabolic syndrome in these patients." (PMID 33129312, 2020). "The other new cross-ethnic validations from our study included rs1173727 with height, rs911119 with cystatin C, rs247616 with the Framingham risk score, and rs646776 with dyslipidemia." (PMID 30704471, 2019). "The results indicated that cystatin C level was independently associated with metabolic syndrome (OR 2.299, 95% CI 1.251–4.225, and P = 0.007)." (PMID 31317040, 2019). "Cystatin C has previously been shown to be elevated in obese subjects, to be secreted by AT in vitro and to be associated with the metabolic syndrome." (PMID 24498934, 2014). "Some studies support an important diagnostic value of cystatin C among patients with metabolic syndrome." (PMID 24639696, 2013). "Since there are controversies regarding the role of cystatin C in the assessment of kidney function, we aimed to assess the clinical significance of serum cystatin C in the early diagnosis of renal injury and its association with dyslipidemia in young T1D patients." (PMID 35208542, 2022). "Another study of circulating adipocyte-EVs is from the 1012 patients with vascular disease, in which the plasma adipocyte-EVs from vascular disease individuals had a high level of cystatin-C, and this adipocyte-EVs–cystatin-C level was associated with the 57% risk of having metabolic syndrome." (PMID 33143043, 2020). "Cystatin C and risk of future metabolic syndrome in the MDC-CC-re-examination-replication-cohort." (PMID 27218257, 2016). "Cystatin C and risk of future metabolic syndrome in the MDC-CC-re-examination-cohort." (PMID 27218257, 2016). "Higher levels of hsCRP (β 5.59; 95% CI 3.00–8.18) and lower HDL-cholesterol levels (β-11.26; 95% CI −18.39 – -4.13) were related to increased EV-cystatin C levels, and EV-cystatin C levels were associated with a 57% higher odds of having the metabolic syndrome (OR 1.57; 95% CI 1.19–2.27)." (PMID 24498934, 2014). "Also, cystatin C serum levels are associated with the risk of cardiovascular events in metabolic syndrome patients." (PMID 24639696, 2013). "Thus, cystatin C could be a useful tool in patients with PCOS who are at high risk of metabolic syndrome and cardiovascular disease." (PMID 24639696, 2013). "A cross-sectional study on 925 dyslipidemic patients showed a progressive increase in cystatin C with the increasing number of metabolic syndrome components." (PMID 35208542, 2022). "The aim of this study was to analyze the effect of T2D, metabolic syndrome, and the atherogenic index of plasma on the levels of cystatin C, CD26, and CD14 proteins in serum exosomes." (PMID 35846887, 2022). "Cystatin C and rs13038305 and incidence of the individual components of the metabolic syndrome in the MDC-CC-re-examination-replication-cohort." (PMID 27218257, 2016). "Logistic regression analysis of creatinine-to-cystatin C ratio level and metabolic syndrome models." (PMID 39205686, 2024).
metabolic syndrome (continued). "Additionally, we observed a significant effect of metabolic syndrome MetS on the increase of exosomal Cystatin C and CD14." (PMID 35846887, 2022). "Moreover, the study evidenced a significant correlation between BOP index and concentration of kidney markers: uric acid, cystatin C, and indicators of metabolic syndrome: concentration of triglycerides, HDL, and glucose." (PMID 34442019, 2021). "Cystatin C may be an independent predictor of metabolic syndrome and therefore valuable for management of NSTE-ACS patients." (PMID 31317040, 2019). "Here, we aimed to investigate the association of cystatin C with metabolic syndrome and cardiovascular outcomes in non-ST-segment elevation acute coronary syndrome (NSTE-ACS) with preserved renal function." (PMID 31317040, 2019). "We recently reported a relationship between plasma levels of cystatin C and incidence of the metabolic syndrome (MetS) among the first 2,369 subjects who participated in the re-examination study of the population-based Malmö and Diet Cancer Cardiovascular cohort (MDC-CC-re-exam)." (PMID 27218257, 2016). "Higher EV-cystatin C levels were significantly related to a 57% higher prevalence of the metabolic syndrome (OR 1.57, 95% CI 1.19–2.27) while no relation was observed between the other EV markers and prevalence of the metabolic syndrome." (PMID 24498934, 2014). "Furthermore, in concordance with studies performed in healthy individuals, we observed a strong relation between EV-cystatin C and the metabolic syndrome in patients with clinically manifest vascular disease." (PMID 24498934, 2014). "This study examined the relationship between cystatin C (CysC) levels and all-cause, cardiovascular disease (CVD), and cancer mortality in US metabolic syndrome (MetS) patients." (PMID 38597157, 2024). "After further adjustments for metabolic syndrome components, fasting insulin, and hs-CRP were made, the differences in the IMT-mean of the cystatin C levels became borderline significant and remained significant across albuminuria categories." (PMID 33129312, 2020). "Patients with and without a metabolic syndrome differ in age, eGFR, serum creatinine and cystatin C concentrations, and plasma interleukin 6 concentration." (PMID 39064306, 2024). "In another study, patients with PCOS were grouped as those with and without metabolic syndrome, and cystatin C correlated with LDL, cholesterol, TG, and total cholesterol." (PMID 35657129, 2022). "EV-cystatin C levels were higher in patients with metabolic syndrome compared to patients without metabolic syndrome (9.84 pg/μg versus 9.97 pg/μg, p = 0.010)." (PMID 24498934, 2014). "In addition cystatin C may be a more sensitive biomarker, when compared to Cr-based GFR estimations, for detecting dyslipidemia-mediated renal impairment in obese children." (PMID 30145854, 2019). "Likewise, as cystatin C increases systolic and diastolic blood pressure are increased too; but the correlation with dyslipidemia is not significant." (PMID 24639696, 2013).
COVID-19 (43 papers, 2020 to 2026). A disease caused by infection with severe acute respiratory syndrome coronavirus 2. "Hub proteins for post-COVID-19 individuals included cytastatin 3 (CST3), Notch homolog 1, translocation-associated (NOTCH1), complement factor H-related 5 (CFHR5), and ST6 beta-galactoside alpha-2,6-sialyltransferase 1 (ST6GAL1)." (PMID 36405747, 2022). "We perform this meta-analysis to determine the association of Cystatin C with the COVID-19 severity." (PMID 36361485, 2022). "In this systematic review and meta-analysis, we searched PubMed, EMBASE, Cochrane library, and Web of Science for studies published until 2nd September 2022 that reported associations between Cystatin C levels and COVID-19 severity." (PMID 36361485, 2022). "Cystatin C has been implicated in severe COVID-19 but, to our knowledge, this is the first report of it being associated with risk of COVID-19 death." (PMID 33587202, 2021). "Cystatin C was positively associated with COVID-19 mortality in univariate analysis and was highly selected by the LASSO models but did not survive multiple adjustment." (PMID 33587202, 2021). "The univariate Cox regression analysis revealed that the COVID-19 patients with elevated cystatin C levels were at a higher risk of death (hazard ratio [HR]: 10.213, 95% CI: 3.542–29.451, and p < 0.001) than those in the normal cystatin C group." (PMID 33828483, 2021). "The highest admission level of serum cystatin C was strongly associated with more severe inflammation, worse organ dysfunction, and worse outcomes in COVID-19." (PMID 33061826, 2020). "As yet, little was known of the relationship between circulating cystatin C levels and disease severity or all-cause death in COVID-19." (PMID 33061826, 2020). "We found that the highest cystatin C level on admission was strongly associated with more severe inflammatory status, worse organ dysfunction, and worse outcomes among patients with COVID-19." (PMID 33061826, 2020). "The predictive value of cystatin C in the prognosis of patients with COVID-19 is rarely reported, but some studies have confirmed that cystatin C can predict the risk of death in patients with COVID-19." (PMID 37217858, 2023). "The underlying interaction between circulating cystatin C and viral infection may provide insight into our better understanding of pathophysiological events in COVID-19." (PMID 34754069, 2021). "However, the logistic regression models adjusting for these confounding factors further revealed that elevated levels of serum cystatin C were independently associated with the risks for critical illness and death in COVID-19." (PMID 33061826, 2020). "Thirdly, even after CKD patients were excluded in the logistic regression models, the highest cystatin C level and ln-transformed cystatin C levels were still independently associated with the risks of developing critically ill COVID-19 and subsequent mortality." (PMID 33061826, 2020). "Secondly, the highest cystatin C level and ln-transformed cystatin C levels were identified in the adjusted analyses as independent risk factors for critical illness and death from all causes in overall patients with COVID-19." (PMID 33061826, 2020). "This study aimed at determining the relationship between baseline cystatin C levels and coronavirus disease 2019 (COVID-19) and investigating the potential prognostic value of serum cystatin C in adult patients with COVID-19." (PMID 33061826, 2020). "This underlying interaction between circulating cystatin C and viral infection may provide insight into our understanding of pathophysiological events in COVID-19." (PMID 33061826, 2020). "Although a biomarker of kidney dysfunction, elevated levels of cystatin C are also associated with an increased risk of cardiovascular events related to endothelial dysfunction due to atherosclerosis and are correlated with severe COVID-19 and COVID-19-related death." (PMID 39774287, 2025).